CYP2F1 (cytochrome P450 family 2 subfamily F member 1)
Description:
May be involved in the metabolism of various pneumotoxicants including naphthalene. Is able to dealkylate ethoxycoumarin, propoxycoumarin, and pentoxyresorufin but possesses no activity toward ethoxyresorufin and only trace dearylation activity toward benzyloxyresorufin. Bioactivates 3-methylindole (3MI) by dehydrogenation to the putative electrophile 3-methylene-indolenine.
Synonyms: C2F1; CYP2F; CYPIIF1
Tractability: Small molecule: it belongs to a druggable protein family. Antibody: UniProt places it where antibodies can reach, with high confidence. PROTAC: a small molecule that binds it is known.
Safety:
Unwanted effects reported when the protein is acted on. In parentheses: how it was acted on, where the effect was seen, and who reports it.
drug toxicity (source: ClinPGx)
Gene: Protein-coding gene on chromosome 19 (41,114,432 to 41,128,381, forward strand). Ensembl gene ENSG00000197446.
Subcellular location: Endoplasmic reticulum membrane; Microsome membrane
Pathways (Reactome):
Metabolism: CYP2E1 reactions; Fatty acids; Xenobiotics
Gene Ontology:
Molecular function: oxidoreductase activity, acting on paired donors, with incorporation or reduction of molecular oxygen, reduced flavin or flavoprotein as one donor, and incorporation of one atom of oxygen; arachidonate epoxygenase activity; heme binding; monooxygenase activity; oxygen binding; iron ion binding; oxidoreductase activity, acting on paired donors, with incorporation or reduction of molecular oxygen
Biological process: naphthalene catabolic process; epoxygenase P450 pathway; xenobiotic metabolic process
Cellular component: intracellular membrane-bounded organelle; cytoplasm; endoplasmic reticulum membrane
Genetic constraint (gnomAD): Loss-of-function variants: 33 observed, 38.19 expected, observed/expected ratio (o/e) 0.86, 90% interval 0.65 to 1.15. The upper end of that interval is the gene's LOEUF score, 1.15, which puts it in group 5 of 6, group 1 being the genes least tolerant of losing a copy. Missense variants: 557 observed, 619.67 expected, observed/expected ratio (o/e) 0.9, 90% interval 0.84 to 0.96. Synonymous variants: 231 observed, 261.57 expected, observed/expected ratio (o/e) 0.88, 90% interval 0.79 to 0.99.
Homologues: Orthologues: chimpanzee CYP2F1 (97% identical), dog CYP2F1 (88% identical), rabbit CYP2F1 (87% identical), pig CYP2F1 (84% identical), rat Cyp2f4 (83% identical), mouse Cyp2f2 (82% identical), guinea pig CYP2F1 (67% identical). Paralogues in human: CYP2A13 (53% identical), CYP2A6 (52% identical), CYP2A7 (51% identical), CYP2C18 (51% identical), CYP2C19 (50% identical), CYP2C8 (50% identical), CYP2C9 (49% identical), CYP2B6 (49% identical), CYP2E1 (48% identical), CYP2S1 (46% identical), CYP2J2 (40% identical), CYP2W1 (39% identical), and 3 more.
Diseases named in the same sentence as CYP2F1 in open-access papers:
CYP2F1 is named in the same sentence as 8 diseases in open-access papers, as found by Europe PMC text mining. Sharing a sentence is not in itself a finding about the gene and the disease. The quoted sentences say what the papers report.
colorectal cancer (1 paper, 2015). A primary or metastatic malignant neoplasm that affects the colon or rectum. "It was previously demonstrated that CYP2F1 is expressed in colorectal cancer and that expression in primary tumors correlated with corresponding metastatic tumors in lymph nodes." (PMID 25765044, 2015).
Hyperglycemia (1 paper, 2023). An increased concentration of glucose in the blood. "BeWo cytotrophoblasts exposed to hyperglycemia displayed increased mRNA expression of ACSL1, HSD11B2, RPS6KA5, and LAP3 and reduced mRNA expression of CYP2F1, and HK2, concomitant with increased levels of: lactate, malonate, and riboflavin metabolites." (PMID 36930661, 2023).
cancer (2 papers, 2017 to 2025). A tumor composed of atypical neoplastic, often pleomorphic cells that invade other tissues. "If one or both of the respiratory enzymes CYP2A13 and CYP2F1 contribute to high-affinity-pathway two, then the reported associations of blood cancers with benzene exposures in ambient populations should take this into account." (PMID 40943470, 2025).
CYP2F1 also shares sentences with these, for which no sentence is quoted: asthma (2 papers); ciliopathies (1); Granuloma (1); lung carcinoma (1); metastatic tumors (1).